EGF (epidermal growth factor)
Diseases named in the same sentence as EGF in open-access papers (continued):
Sharing a sentence is not in itself a finding about the gene and the disease.
tumor (continued). "Increased proliferation and angiogenesis by EGFR are thought to be caused by the binding ligands TGFα and EGF, which have shown to function as chemoattractants for endothelial cells and promote the expression of VEGF by tumor cells." (PMID 31303863, 2019). "The results indicated that both TGFβ1 receptor and Smad2 were involved in the process that MSCs facilitated the expression of TGFβ1 and EGF in VX2 tumor tissue." (PMID 31528217, 2019). "Previous studies have been found that abalone visceral extracts showed remarkable inhibitory effect on tumor progression by regulating the expressions of tumorigenic factors, such as Cox-2, EGF, VEGF and FGF." (PMID 31022939, 2019). "For example, epidermal growth factor (EGF) modulates the motility machinery of EGF receptor (EGFR) expressing tumor cells that includes polarized signaling, cell adhesion, and cytoskeletal remodeling." (PMID 31428691, 2019). "In our study, damaged Cargo recognition is likely to promote the intenity of cancer signaling like EGF and Wnt, and then resulted in overflow of tumor spreading." (PMID 31219228, 2019). "The second term characterizes the logistic growth of the tumor cell population which depends on the local concentration of EGF." (PMID 31157216, 2019). "EGF–EGFR and its signaling pathway have been reported to be associated with tumor progression, especially in androgen-independent PCa metastasis." (PMID 31555577, 2019). "Co-administration of an excess (15 μg) of EGF to block uptake by EGFR on hepatocytes improved tumour uptake from 2.8%ID/g to 3.9%ID/g." (PMID 31659527, 2019). "When the EGF concentration in the lymph node exceeds the threshold value eg0*, the tumor cells increase their proliferating rate." (PMID 31157216, 2019). "The levels of EGF protein present into the tumor microenvironment were also measured by ELISA using tumor cell extracts obtained from mice bearing B16-OVA, MC38, PM299L, or Hepa129 cell line derived tumors." (PMID 31921216, 2019). "Activation of the EGFR signal transduction pathway by EGF is known to play a role in cellular motility and size increase in the tumor aggressiveness." (PMID 31250984, 2019). "Upon EGF stimulation, β-catenin escaped from the degradation in cytoplasm and translocated into the nucleus to transactivate expression of genes involving in tumor invasion in a mechanism distinct from Wnt-dependent canonical signaling." (PMID 30918250, 2019). "For example, more specific targeting of tumors can be achieved by conjugating tumor-specific recognition molecules such as transferrin, folic acid, epidermal growth factor (EGF), or any number of monoclonal antibodies to the surface of GNPs." (PMID 31024882, 2019). "Our data suggest that upregulation of NAB2, a corepressor of EGR1, permits EGF-mediated cancer invasion during conditions of EGR1 overexpression through the transactivation of Sp1-dependent tumor-promoting genes." (PMID 30845713, 2019). "Of the EGFR ligands, amphiregulin, BTC, EGF, and TGFα were expressed in the cytoplasm of 50%, 76%, 70%, and 73% of the tumours respectively." (PMID 30899442, 2019). "Typically, once cells are dissociated from the patient tumor tissue, they are cultured as neurospheres in neurobasal medium supplemented with epidermal growth factor (EGF) and fibroblast growth factor (FGF2)." (PMID 31574953, 2019). "In fact, genistein inhibits epidermal growth factor (EGF) activity while it activates the FOXO3 tumor suppressor gene and inhibits the insulin-like growth factor-I receptor (IGF-I)." (PMID 31344966, 2019).
tumor (continued). "LPNs were designed for targeted delivery of RSV and DTX to the mitochondria of tumor cells by conjugating the epidermal growth factor (EGF) and stearic acid (SA) with polyethylene glycol (PEG)." (PMID 31349656, 2019). "This supports the conclusion drawn from simulations of the continuous model which implies that the administration of EGF can result in the elimination of the tumor by anti-PD-1/PD-L1 agents." (PMID 31157216, 2019). "A variety of endogenous factors, such as vascular endothelial growth factor (VEGF), basic fibroblast growth factors (bFGF), epidermal growth factor (EGF) and EETs, promote angiogenesis and contribute to the development of tumours." (PMID 31791289, 2019). "In patient 4, a minor clone of cells reflected high expression of VEGF, followed by lower expression of EGF in the central of tumor with notable co-expression." (PMID 31565199, 2019). "The importance of EGF for increased ITGA5 expression in tumor cells was confirmed, since addition of an EGF-neutralizing antibody to the suspension coculture attenuated ITGA5 expression in MUs." (PMID 30710055, 2019). "We demonstrate here that macrophages in the peritoneum rather than the primary tumor site play a critical role in supporting metastatic tumor cells to develop by producing EGF and VEGF." (PMID 31632482, 2019). "Given the importance of Akt for tumor survival and growth, future studies are needed to explore the crosstalk between EGF-EGFR and CXCL12-CXCR7 in the MAPK pathway." (PMID 30935067, 2019). "Macrophages on the peritoneum produce growth factors, for instance, VEGF and EGF, to support angiogenesis and tumor growth, respectively." (PMID 31632482, 2019). "where the first term in the right-hand side of this equation describes EGF diffusion, the second term represents EGF consumption by tumor cells, and the third term describes its degradation." (PMID 31157216, 2019). "In the tumor microenvironment, tumor stroma surrounding PCa cells is enriched in fibroblasts that secrete AR-activating factors, such as EGF, FGF-7/KGF, IGF-1, and IL-6." (PMID 31484364, 2019). "In the regime of tumor escape, the ratio of dormant cells to proliferating cells becomes higher as the EGF concentration decreases." (PMID 31157216, 2019). "Recently, it was reported that the education of LECs with tumor-conditioned medium enhances the secretion of lymphangiocrine factors, including EGF and PDGF-BB, that promote tumor cell proliferation, angiogenesis and pericyte infiltration." (PMID 31182803, 2019). "Then, we introduce the immune response and quantify the combined effect of PD-1/PD-L1 inhibition and EGF concentration on the outcome of the tumor-immune interaction in the LN." (PMID 31157216, 2019). "Herein, we reported that the tumor suppressor FBXW2 is an ubiquitin ligase responsible for β-catenin degradation following EGF stimulation." (PMID 30918250, 2019). "In PC agents, we not only took into account of the androgen-independent pathway (triggered by EGF and WNT5A), but also DHT-mediated androgen-dependent signaling to determine the internal factors-associated tumor cell proliferation." (PMID 31504033, 2019). "Both models predict that the administration of EGF can promote the elimination of the secondary tumor by PD-1/PD-L1 blockade." (PMID 31157216, 2019). "In this present study, we examined the expression of TAM subsets in OSCC tissues and the relationship between the expression of TAM markers and EGF production and tumor progression." (PMID 31601953, 2019). "In both continuous and hybrid models, we have demonstrated the existence of a threshold value for the EGF concentration in the LN that separates the regimes of tumor evasion and tumor elimination." (PMID 31157216, 2019). "In skin diseases, epidermal growth factor (EGF)-induced MMP-1 expression in skin fibroblasts has been shown to be related to the deregulation of matrix metabolism." (PMID 31752262, 2019).
tumor (continued). "In this review, we focus on the suppression mechanisms of PDCD4 protein that is induced by the tumor promotors EGF and TPA, and in the inflammatory conditions." (PMID 31075975, 2019). "Our data suggest that NAB2 upregulation facilitates EGF-mediated cancer cell invasion through the transactivation of Sp1-dependent tumor-promoting genes." (PMID 30845713, 2019). "Collectively, our results identify the promotion of epidermal growth factor signaling through cadherin maintenance as a critical tumor-promoting function of membranous β-catenin in HCC." (PMID 31015417, 2019). "We also examined EGF and Bnl signal transduction in tumor and suppressed tumor discs by staining with anti-dpERK antibody." (PMID 31568500, 2019). "Since the EGFR pathway represents a possible target for cancer treatment, we quantify the effect of the EGF concentration in the lymph node (eg0) on the development of the tumor." (PMID 31157216, 2019). "The differential activity of EGF in normal and tumor cells illustrates differential wiring of TRAIL signaling upon oncogenic transformation." (PMID 31333662, 2019). "More importantly, β-catenin localization and tumor progression also positively fed back on EGF/EGFR-attenuated AJAP1 expression." (PMID 31171012, 2019). "In the presence of EGF that is also present in the tumor microenvironment, EGFR-directed antibodies showed a paradoxical stimulatory effect on RAS mutant cells." (PMID 32039027, 2019). "MTSS1, another mRNA regulated by this lncRNA has been well documented as a tumor suppressor controlling migration and invasion in OC with involvement in the EGF pathway." (PMID 31842477, 2019). "EGCG binds to various proteins and both DNA and RNA molecules, it also inhibits binding of ligands and tumor promoters to their receptors in the cell membrane, and the receptor signaling pathway of epidermal growth factor (EGF)." (PMID 30934576, 2019). "We begin by studying the regime of tumor escape in the case where the concentration of EGF in the LN is equal to GF0 = 100nM and we introduce 50 tumor cells to the computational domain as an initial condition." (PMID 31157216, 2019). "EGF/EGFR‐induced signaling is associated with organ morphogenesis, maintenance, and repair, as well as tumor invasion and metastasis." (PMID 31026363, 2019). "Then, we consider the immune response and we quantify the effects of immunosuppression and local EGF concentration on the fate of the tumor." (PMID 31157216, 2019). "Several studies indicated that TAMs secrete various kinds of cytokines including growth factor, for example EGF and IL-6, and EGF strongly induces tumor cell proliferation." (PMID 31601953, 2019). "And the remodeling of tumor interstitial microenvironment was shown by the expression of TGFβ1, epidermal growth factor (EGF), fibroblast activation protein alpha (FAPa), matrix metalloprotein 9 (MMP9)." (PMID 31528217, 2019). "We have quantified by ELISA the EGF levels in different tumors types isolated from mice previously inoculated with tumor cell lines." (PMID 31921216, 2019). "TAMs secrete extensive amounts of proangiogenic growth factors including epidermal growth factor (EGF) are considered as the most potent source of EGF in tumor microenvironment." (PMID 31601953, 2019). "The regime of tumor-immune equilibrium can only be observed when the concentration of EGF in the LN is reduced." (PMID 31157216, 2019). "Recently, endogenous ligands such as epidermal growth factor (EGF) have shown great potential for targeting EGFR on tumor cells." (PMID 31754382, 2019). "Similar to our previous experiments, EGF further enhanced tumor cell MAPK pathway activity and PD‐L1 expression, which was counteracted by erlotinib and selumetinib, without influencing MHC‐I." (PMID 30972766, 2019). "The increased levels of IL10, VEGF, and EGF in TAMs, in turn, promote treatment resistance by enhancing immune suppression and tumor proliferation." (PMID 31504033, 2019).
tumor (continued). "In particular, we have studied the role of the immuno-suppressive mechanism in the dynamics of tumor progression in tissues with different EGF concentrations." (PMID 31157216, 2019). "In the continuous model, the kinetic rates of tumor dormancy and activation depend on the local concentration of EGF and the density of immune effector T-cells." (PMID 31157216, 2019). "Here, TAMs perform varied flagrant functions like secreting tumor inducing factors like EGF, creating an immunosuppressive environment and promoting angiogenesis while also maintaining tumor related inflammation and inducing metastasis." (PMID 30925924, 2019). "In general it starts with the production of CSF-1 from the tumor cells which induces EGF production in the TAMs." (PMID 30925924, 2019). "For example, all imaging probes based on EGF have much higher uptake in liver than in tumors or the tumor-to-liver ratio is close to one, which precludes the use of such tracers for imaging of EGFR expression in hepatic metastases." (PMID 30231504, 2018). "VEGF and EGF are commonly released by innate immune cells, but tumor cells can also secrete VEGF in an autocrine manner, thereby stimulating cancer stemness." (PMID 30577587, 2018). "Previously, XMD8-92 was reported to inhibit EGF-induced ERK5 phosphorylation in multiple tumor cell lines." (PMID 29416614, 2018). "EGCG inhibits the binding of various ligands, tumor promoters, and epidermal growth factor (EGF) to their receptors in the cell membrane, which is called the “sealing effects” of EGCG." (PMID 30126206, 2018). "For better tumor targeting and accumulation of PS at the region of the tumor, gold nanoparticles were complexed with peptides for both epidermal growth factor and transferrin receptors that were over-expressed on the surface of polymorphic glioblastoma." (PMID 30960886, 2018). "Specific targets are the receptors for vascular endothelial growth factor (VEGF), platelet-derived growth factor (PDGF) and epidermal growth factor (EGF), which are all involved in (tumor) angiogenesis." (PMID 30460241, 2018). "In return, microglia secrete tumor proliferation promoting factors including epidermal growth factor (EGF) and vascular endothelial growth factor (VEGF), TGF-β, arginase-1 (ARG1), and IL-10." (PMID 30319362, 2018). "Several proangiogenic factors such as angiopoietin 2 (ANG-2), EGF, bFGF, keratinocyte growth factor, IGF-1, TGF-β, TNF-α and interleukins (IL-1, IL-8, IL-12 and IL-17) have been implicated in hypoxia-associated tumor refractoriness to anti-VEGFR therapy." (PMID 29455658, 2018). "Tumor-educated LECs were recently shown to secrete EGF, which contributed to increased cancer cell proliferation and tumor growth in vivo, as well as PDGF-BB, which enhanced pericyte infiltration and angiogenesis." (PMID 29976154, 2018). "A diversity of angiogenic factors (such as VEGFA, PDGFB, bFGF and EGF) secreted from tumour cells have been reported to play an important role in tumour angiogenesis." (PMID 30584257, 2018). "Further, the IBA1+ and CD163+ immune brain cells express EGF in the tumor border and thus stimulate the tumor cells to invade the parenchyma." (PMID 30123112, 2018). "Transforming growth factor alpha (TGFα), FGF-2, and EGF were increased in the G59 PDX group compared to the G68 PDX group suggesting a more angiogenic tumor profile in the less cachectic G59 PDX group." (PMID 30513792, 2018). "Invadopodia are preferentially formed in the region of tumor cells exposed to an EGF gradient, and these invadopodia are required for chemotactic sensing." (PMID 29463791, 2018). "In accordance, the malignant lesion can secrete various factors such as bFGF, TGF-β, PDGF, EGF creating tumor microenvironment by interacting through other growth factors receptors (EGFR)." (PMID 29499765, 2018). "Transcriptomic analysis of the tumor has shown upregulation of various oncologically relevant pathways, including EGF/ErbB, Aurora Kinase A, pak21 and wnt." (PMID 29535801, 2018).
tumor (continued). "Concurrently, M2 cells release other growth factors, including EGF and TGFβ, that promote tumor proliferation and the migration of tumor cells away from the hypoxic niche." (PMID 29732370, 2018). "CAFs produce higher levels of tumor-promoting factors, such as HGF, FGF, TGFβ, PDGF, VEGF, and EGF, as compared to normal fibroblast; these factors act in a paracrine manner on the cognate receptors expressed on adjacent tumor cells." (PMID 30544501, 2018). "The three proteins (MMP-8, TIMP-4 and EGF) that following a decrease during tumor inhibition also showed evidence for an increase during progression are involved in cancer cell survival, proliferation and migration." (PMID 30592740, 2018). "Heterogeneity within individual patient biopsies concerning tumor viability and proliferation in response to supplements EGF, hydrocortisone and folic acid, is observed." (PMID 29861851, 2018). "EGF is an effective mitogenic factor that can stimulate cell division and proliferation in multiple tissues and promote infiltration and metastasis of tumor cells." (PMID 30671125, 2018). "The most appropriate view seems that the growth under serum-free conditions in the presence of EGF and bFGF allows a “dedifferentiation” of tumor cells." (PMID 30279357, 2018). "In the PyMT breast cancer mouse model, CSF-1 produced by tumor cells and EGF secreted by TAMs results in the migration of both macrophages and cancer cells along collagen fibers and intravasation into the blood vessels." (PMID 30356656, 2018). "Termed invadopodia, these extensions are formed by the selective stimulations of tumor cell-expressed platelet-derived growth factor and epidermal growth factor." (PMID 30002653, 2018). "We have previously demonstrated that in primary FLC tumor tissue there are consistent changes in various oncologically relevant pathways such as EGF/ErbB2, Aurora Kinase A and wnt signaling pathways." (PMID 29535801, 2018). "Injecting high concentrations of labeled EGF into the tumor-bearing mice increased the number of EGF receptors found in early endosomes to levels similar to that seen in cultured cells also treated with high ligand concentrations." (PMID 29300164, 2018). "This work indicated that maintaining an EGF and CSF-1 paracrine loop between tumor cells and TAMs was required for the migration of breast tumor cells to the surrounding tissue and blood vessels." (PMID 29599778, 2018). "AP-1 is a downstream convergence point of different signaling cascades and is required for EGF-induced cell transformation and tumor development." (PMID 29463844, 2018). "Several signaling pathways (such as those of TGF-β, Wnt, EGF, Hedgehog, Notch, and ROS) can activate oncogenes and inactivate tumor suppressors, thereby inducing tumorigenesis and tumor progression." (PMID 29636841, 2018). "Accumulating studies have demonstrated that miRNAs play critical roles in EGF signaling regulation, tumor initiation, cell proliferation and apoptosis." (PMID 30464258, 2018). "Some of these factors and others can also stimulate tumor proliferation and survival (e.g. EGF, PDGF, TGF-β1, HGF and FGF-2)." (PMID 29728948, 2018). "Contemporarily, BMDCs are attracted in PDAC stroma by growth factors as fibroblast activation protein (FAP), PDGF, TGF-β1, VEGF, and EGF produced by tumor cells and participate to PSC activation." (PMID 30662458, 2018). "TAMs secrete EGF, FGFs, and VEGFs that promote tumor cell proliferation, fibroblast activation and angiogenesis." (PMID 30356678, 2018). "A well-characterised example of this interaction is through a paracrine loop involving M-CSF released from tumour cells, and epidermal growth factor (EGF) released by TAMs62." (PMID 30054470, 2018). "TAMs stimulate tumor distribution through interaction with the receptor activator of the NF-κB ligand (EGF or RANKL) secreted by tumor cells." (PMID 29988496, 2018).